ULK1 (unc-51 like autophagy activating kinase 1)
Diseases named in the same sentence as ULK1 in open-access papers (continued):
Sharing a sentence is not in itself a finding about the gene and the disease.
tumor (continued). "In HepG2 tumor tissues treated with HDIs, FOXO1 and ULK1 expression was significantly elevated compared with the control group, but when mice were treated with HDIs combined with AS, FOXO1 and ULK1 expression in tumor tissue was significantly reduced to levels close to that of the control group." (PMID 32929346, 2020). "Regarding tumor cell survival, the resistance to metabolic stress induced by TMEM74 overexpression was counteracted by ATG5, ATG7, ATG16L1, ATG3 and ATG10 deficiencies but not the BECN1 and ULK1." (PMID 29048433, 2017). "Unlike the increased phosphorylation of Ulk1, both LCI and LCII diminish dramatically in Tet2-deficient mouse livers, which is confirmed in TET2 KO tumor cells, suggesting that Tet2 might promote activation of autophagy in both mTORC1-dependent and -independent manners." (PMID 37550284, 2023). "Results from 30 cases of patients with HCC also showed that tumor cellular levels of miR-26a and miR-26b are significantly downregulated as compared with the corresponding control tissues and negatively correlated with the protein level of ULK1 but are not correlated to the mRNA level of ULK1." (PMID 28079894, 2017). "SW620 cells showed elevated total ULK1 levels, whereas no significant changes were noted in the HCT116 or non-tumor cells." (PMID 39404412, 2024). "AMPK-dependent activatory phosphorylations of Ulk1 and Beclin1, which are involved in autophagy initiation, were increased in vehicle and (−)-JQ1-treated tumor-bearing mice, but not in the (+)-JQ1-treated animals." (PMID 29167426, 2017). "Given mutant gene or protein is usually amplified during tumor development, it may explain why PDAC cells lacking ULK1/2, as mentioned here in our study, had impaired tumorigenic phenotypes both in vitro and in vivo." (PMID 34345207, 2021). "In contrast, ULK1 inhibitor SBI-0206965 and/or ATG13-KO alone were not strong enough to inhibit tumor growth as efficiently as DKO, indicating that targeting ULK1 and ATG13 together might be a potential anticancer strategy." (PMID 32516310, 2020). "Our data supports the hypothesis that in MF cells, uniquely, higher GZ17-6.02 concentrations regulate novel mechanisms, independent of the ATM-AMPK-mTORC1/ULK1 pathway we have previously observed using GZ17-6.02 in solid tumor cells, to further enhance macroautophagy and MF tumor cell killing." (PMID 38329728, 2024). "However, we found that autophagy inhibition by CQ or ULK1 depletion did not increase the expression of CCL5 or CXCL10 in NSCLC cells, suggesting that autophagy inhibition could not promote the infiltration of NK cells into NSCLC tumor." (PMID 35002511, 2022).
cancer (198 papers, 2010 to 2026). A tumor composed of atypical neoplastic, often pleomorphic cells that invade other tissues. "Reducing m7G levels decreases the translation of certain cancer-promoting transcripts in the regulatory associated protein of mTOR complex 1 (RPTOR)/ unc-51 like autophagy activating kinase 1(ULK1)/autophagy pathway." (PMID 39791162, 2025). "Polymorphisms in the uncoordinated 51-like kinase 1 (ULK1) gene are associated with susceptibility to multiple diseases, including neurodegenerative disorders and specific cancer types." (PMID 40995090, 2025). "Similar to APG-115, the depletion of ULK1 notably enchanced the susceptibility of cancer cells to idasanutlin." (PMID 39215364, 2024). "To delve deeper into how GSDME cleavage is promoted in ULK1-deficient cancer cells, we performed qPCR and western blot analysis." (PMID 39215364, 2024). "We further investigated why the combination of an MDM2i treatment and ULK1 deficiency effectively kills cancer cells." (PMID 39215364, 2024). "Various studies have detailed the structural characteristics and biological functions of ULK1, as well as its regulatory pathways in autophagy and its association with different diseases, including cancer." (PMID 38286802, 2024). "All these results suggested that NLRP3-caspase signaling axis was activated in ULK1 deficiency cancer cells." (PMID 39215364, 2024). "More importantly, evidence clearly points to a convergent role of Copper in autophagy of cancer cells 53, 54, implying a functional association and connection between ULK1/2 and the Copper complex." (PMID 34345207, 2021). "Dysregulation of ULK1 has been implicated in numerous diseases such as cancer, diabetic disease, and neurodegeneration, mostly via regulation of autophagy." (PMID 34421918, 2021). "What’s more, we have observed that decreased ubiquitination and increased stability of the metabolic related molecules, such as PDK1, NRF2, ULK1 and phosphoglycerate kinase 1, are associated with chemoresistance in various cancers." (PMID 33004065, 2020). "Chaperone Lon is evolving to be recognized for its cyto-protective role in cancer, which is supported by the observation that ULK1 association with the ATPase domain of Lon is important for its maintenance and kinase activity for mitophagy and cell survival under hypoxia." (PMID 36927870, 2023). "Our data uncovered the mechanism underlying mTOR overactivation in cancers and suggested that targeting mTOR/ULK1/autophagy could be an effective strategy for METTL1 overactive ESCC treatment." (PMID 35304469, 2022). "Unc-51-like kinase 1 (ULK1), a central regulator of autophagy, has emerged as a potential therapeutic node in cancer but remains poorly understood in TNBC." (PMID 41774346, 2026). "Collectively, these results delineate a mechanistic pathway in which LSPs‐mediated mechanical disruption of lysosomes activates Gal3 recruitment and subsequent Trim16/ULK1 engagement, leading to excessive autophagy and cancer cell death." (PMID 41082270, 2026). "Induces autophagy-associated apoptosis in cancer cells.Inhibits the PI3K/AKT/mTOR pathway by reducing p-PI3K expression.Increases ROS production, leading to AMPK activation, upregulation of ULK1, and phosphorylation of Beclin-1, thereby promoting autophagy." (PMID 41211420, 2025). "MRT403 is the first ULK1-specific inhibitor approved for preclinical animal studies in cancer and other diseases." (PMID 40001518, 2025). "The combination of wogonin and oxaliplatin demonstrated a possible reduction in cancer cell survival through alteration of phospho‐ULK1 (Ser555) and phospho‐ULK1 expression in the zebrafish xenograft model." (PMID 41164269, 2025).
cancer (continued). "Of note, another study also highlighted the significance of ULK1 S556 phosphorylation in activating autophagy in RAS-mutant cancer cell lines." (PMID 40055523, 2025). "Beyond its canonical role in autophagy initiation, ULK1 regulates various cancer-related processes—including metabolic reprogramming, redox homeostasis, cell cycle progression and immune modulation—through direct phosphorylation of diverse downstream targets." (PMID 41408407, 2025). "In contrast to previous studies that independently examined autophagy and Notch1 signaling in BE or other cancers, our findings mechanistically connect these two processes through ULK1, a key autophagy initiator." (PMID 40629071, 2025). "Collectively, these findings indicate the multifaceted, autophagy-independent roles of ULK1 in cancer progression." (PMID 41408407, 2025). "While the therapeutic targeting of ULK1/2 is emerging as a promising strategy in cancer, most available inhibitors remain at the preclinical research stage." (PMID 40611330, 2025). "Recent studies have shown that the dysregulation of autophagy-related genes, such as ATG12 and ULK1, plays a crucial role in the progression of various cancers, including gastric cancer, acute myeloid leukemia, renal cell carcinoma, and BC." (PMID 40066127, 2024). "Studies have shown that TRAF6 induces ubiquitination of ULK1 by Lys63 chain, which stabilizes the expression of autophagy protein ULK1 and promotes the occurrence of autophagy, thereby promoting the progression of malignant tumors." (PMID 38135696, 2024). "Numerous studies have emphasized that altering ULK1 can impact both autophagy and apoptosis, affecting the trajectory of cancer growth and its sensitivity to treatments." (PMID 38240686, 2024). "We also found that the anti-cancer effect of ICA was associated with the promotion of autophagy, possibly via ICA activation of the AMPK/mTOR/ULK1 pathway." (PMID 38355608, 2024). "Knockout of ULK1 significantly increased the sensitivity of cancer cells to APG-115, as determined by MTT and flow cytometry assays." (PMID 39215364, 2024). "As expected, measurement of overall intracellular ROS levels confirmed a significant increase in cancer cells following ULK1 depletion." (PMID 39215364, 2024). "ULK1 specifically plays a key role in initiating and controlling autophagy, increasing the chances of cancer cell survival." (PMID 39650649, 2024). "Inhibition of ULK1 has a therapeutic potential as long as its function is properly characterized in specific cancers." (PMID 38976168, 2024). "The suppression of the mTOR pathway increases autophagy directly since mTOR inhibits autophagy through Ulk1 and reduces the translation of proteins, cellular growth, and proliferation, impacting cancer." (PMID 37534085, 2023). "The inhibition or activation of ULK1 is often effective in overcoming cancer drug resistance to tyrosine kinase inhibitors (TKI), selective BRAF inhibitors, 5-fluorouracil (5-FU), KRAS drugs, doxorubicin, tamoxifen, and crizotinib." (PMID 36671802, 2023). "Our data reveals that Caprin-1 induces the dephosphorylation of ULK1 and triggers autophagosome fusion that maintains cancer cells growth." (PMID 38082307, 2023). "ULK1 has been shown to accelerate cancer cells growth, however, we found a positive correlation between higher level of ULK1 and extended prognosis in PDAC patients, suggesting ULK1 or autophagy associated heterogeneity in different cancer types." (PMID 38082307, 2023).
cancer (continued). "Dozens of small molecule compounds targeting ULK1/ULK2-mediated autophagy in cancer have been tested." (PMID 36671802, 2023). "It has been shown that cancer cells can resist NK cell-mediated killing by decreasing granzyme B levels via autophagy, more specifically via activation of ULK1." (PMID 35203256, 2022). "Several autophagy inhibitors have been developed as potential anti-cancer drugs such as chloroquine or ULK1 inhibitors, exploiting metabolic requirement of cancer cells." (PMID 35237600, 2022). "The results of Western blotting suggested that the expression of autophagy-related proteins LC-3, ULK1, and Beclin-1 was decreased in cancer tissues, while CDM treatment led to a dose-dependent increase in their expression." (PMID 35126526, 2022). "Considering the dual role of autophagy, differential strategies have been employed using ULK1 inhibitors or activators depending on the cancer type." (PMID 36291728, 2022). "In consideration of the functions of ULK1 in autophagy, more work is needed to discover the specific ULK1 inhibitors for potential cancer therapeutic effects in animal models and clinical trials." (PMID 36034776, 2022). "Cat D KO/ KD decreased the phosphorylation of ULK1 at S757 and increased the phosphorylation of ULK1 at S777 in all tested cancer cell lines." (PMID 35715412, 2022). "ULK1 constitutes an optimal target for autophagy inhibition, and ULK1 inhibitors are being tested as anticancer agents, showing interesting results on some types of cancers." (PMID 34885651, 2021). "Since YAP is a key coactivator in determination of cancer cell fate, such molecular mechanism necessitates the participation of multiple oncogenic events to coordinate with ULK1/2 for the fine tuning of YAP function under pathological circumstances." (PMID 34345207, 2021). "To further validate our data in a cellular model that mimicking well the anti-neoplastic aspects of clinical patients, we tested the efficacy of ULK1/2 blockade combined with 2-DG or 3-BP using a pancreatic patient-derived cancer cell (PDC)." (PMID 34345207, 2021). "MicroRNAs modulate autophagy through their effects on various autophagy regulatory proteins, such as ULK1, the principal inducer of this process, which has been identified as a direct target of different microRNAs in various types of cancer." (PMID 33572255, 2021). "As an autophagy initiation factor, ULK1 has been proven to promote autophagic flux and inhibit cancer progress and metastasis." (PMID 34671559, 2021). "Several studies reported that ULK1 inhibits cancer metastasis by promoting autophagy and interacting with the mTOR/AMPK pathway." (PMID 34671559, 2021). "In line with mTOR inhibition, ULK1 is dephosphorylated on Ser757, and autophagy is consequently upregulated, stabilizing the diapause of mESCs, as well as the dormancy of cancer cells." (PMID 34832087, 2021). "Recent evidence suggests that GSK-3β stimulates autophagy through phosphorylation of Ulk1 at Ser405 and Ser415 in neurons and cancer cells." (PMID 34778891, 2021). "Neferin, a natural alkaloid of Nelumbo nucifera, has been shown to induce autophagy-mediated cell death in a panel of cancer cells containing cell lines resistant to apoptosis, activating the ryanodine receptor and ULK1/PERK/mTOR/AMPK signaling cascades." (PMID 33233671, 2020). "Together, these findings reveal that the AMPK/ULK1/LC3B pathway plays an important role in mediating the anti-cancer effects of SH003 in GC cells." (PMID 32879309, 2020). "Overexpression of ULK1 is negatively correlated with prognosis in various cancers, including colorectal cancer, breast cancer, human nasopharyngeal carcinoma, and esophageal squamous cell carcinoma." (PMID 32393312, 2020). "Although uncoordinated 51-like kinase 1 (ULK1), which plays a central role in the autophagy pathway, has emerged as a novel therapeutic target for various cancers, its role in FLT3-ITD AML remains elusive." (PMID 32393312, 2020).
cancer (continued). "Our findings demonstrate a synergistic anticancer effect in response to combined treatment with NUAK1 inhibitor (WZ4003) and ULK1 inhibitor (SBI-0206965) in different types of cancer cells." (PMID 32873786, 2020). "The ability of WZ4003 to induce cell death in combination with ULK1 inhibitors was assessed in different cancer cell lines." (PMID 32873786, 2020). "Specific autophagy inhibitors have both clinical potential for the treatment of autophagy-dependent cancers but can also act as key tools to study the function of ULK1 and autophagy in different contexts." (PMID 33109685, 2020). "Cancers with low NEDD4L expression tend to display enhanced mitochondrial metabolic functions due to ULK1-mediated autophagy." (PMID 31959741, 2020). "Our results can guide the selection of ULK1 as a target in certain cancer types, suggest which readouts to study for experimental research in cancer cellular biology, and provide knowledge for pharmacological or clinical-oriented efforts." (PMID 32913252, 2020). "Of note, deletion of ULK1 increases chromosome instability and cytotoxicity following treatment with paclitaxel, resulting in significant impairment of cancer cell growth." (PMID 32033142, 2020). "Given the key role of ULK1 in autophagy initiation and the fact that numerous cancer cells depend on autophagy for survival, inhibition of ULK1 with small-molecule inhibitors makes it a promising target for cancer drug discovery." (PMID 33109685, 2020). "In this work, we reviewed recent studies related to the effects of ULK1 on the regulation of autophagy and the development of drug resistance in cancers, with the aim of clarifying the mechanistic underpinnings of this therapeutic target." (PMID 32033142, 2020). "We here applied a framework which links -omics data to structural protein ensembles to study ULK1 alterations from genomics data available for more than 30 cancer types." (PMID 32913252, 2020). "Autophagy is initiated by the ULK1 complex, and inhibition of ULK1 has shown encouraging results in cancer therapy." (PMID 32792960, 2020). "ULK1 is crucial in the regulation of autophagy in cancer cells; the phosphorylation of ULK1 alters the activity of autophagy." (PMID 32033142, 2020). "In this context, we started a series of studies in which we have been linking data from cancer genomic initiatives with structural ensembles to understand the impact of cancer-related alterations in autophagy proteins, such as ULK1 and LC3 proteins." (PMID 32587856, 2020). "Even though a better understanding of the individual factors contributing to the effect autophagy has on cancer is needed, mTORC1 and its associated regulators of autophagy, ULK1 and AMPK, represent attractive targets for cancer therapy." (PMID 30764584, 2019). "In conclusion, we describe a new mechanism based on mitochondrial ROS accumulation and ULK1 phosphorylation on Ser-555, by which p38α can induce autophagy and influence cancer cell fate decisions in response to stress." (PMID 31092814, 2019). "ULK1 has been shown to be upregulated in several cancers, which correlated with poor prognosis and treatment resistance." (PMID 31635099, 2019). "Mechanistically, p38Tbeta; MAPK mediates cancer-provoked autophagy activation by upregulating Atg8 orthologues LC3b and Gabarapl1 as well as by activating ULK1." (PMID 31225455, 2018). "The current study identifies p38β MAPK as a key mediator of cancer-induced autophagy activation in skeletal muscle, through activating ULK1 as well as upregulating C/EBPβ-controlled LC3b and Gabarapl1 genes." (PMID 31225455, 2018). "The experimental evidence for involvement of ATG13, ATG101 and FIP200 in cancer is less clear, but given their critical role in regulating ULK1 function, they are likely to play a similar role." (PMID 29233870, 2017). "In accordance with chi-square test, the Ulk1 overexpressed cancers have higher recurrence rate compared with that with low level of Ulk1." (PMID 28410240, 2017).